EPCAM (epithelial cell adhesion molecule)
Diseases named in the same sentence as EPCAM in open-access papers (continued):
Sharing a sentence is not in itself a finding about the gene and the disease.
ovarian carcinoma (continued). "Catumaxomab, which targets EpCAM andCD3, was approved for the intraperitoneal use in ovarian cancer patients and others with malignant ascites and EpCAM+ tumours in Europe in 2009." (PMID 32937961, 2020). "In this study, we report the identification of the EpCAM-claudin-4 or −7-CD82 complex in the ovarian cancer progression and metastasis in vitro." (PMID 32091301, 2020). "In vitro binding specificity experiments confirmed that the binding of [125I]I-PIB-Ec1 to OVCAR-3 and SKOV-3 ovarian cancer cells was EpCAM-mediated." (PMID 32392820, 2020). "While EpCAM-positive exosomes can be detected in both patients with benign ovarian disease and ovarian cancer, the exosomal miRNA profiles were remarkably distinct in cancer patients and patients with benign disease." (PMID 32226524, 2020). "In the present study, we analyzed CTCs levels in patients with high grade ovarian cancer using both direct and indirect quantification strategies after an EpCAM-based immune-enrichment." (PMID 32423054, 2020). "Several therapeutic approaches for targeting EpCAM in lung, gastric, colorectal, breast, and ovarian cancers have been evaluated in clinical trials." (PMID 32392820, 2020). "EpCAM(+) T-EVs enhance malignant ovarian tumour development, and are significantly more numerous in patients with malignant ovarian tumours than in females with benign ovarian disorder or healthy control subjects." (PMID 33081785, 2020). "More than 90% of metastatic lesions of malignant ovarian tumors, as well as many other carcinomas, overexpress EpCAM relative to normal epithelial cells and normal mesothelium." (PMID 32630661, 2020). "Tumour tissues from endometrial or ovarian cancer patients were homogenised and EpCAM+ tumour cells were sorted and tested for VISTA expression." (PMID 30382166, 2019). "EpCAM is also considered as an ovarian cancer tissue specific protein which is used for isolation of ovarian cancer derived exosomes." (PMID 31718609, 2019). "Paclitaxel significantly enhanced the expression of EpCAM in HEY ovarian cancer cell line and it was significantly suppressed by the addition of Dasatinib." (PMID 30791462, 2019). "More recently, we also demonstrated a crucial role for EpCAM in regulating platinum-based chemotherapy resistance in patients with ovarian cancer." (PMID 31261739, 2019). "They found that EV-associated EpCAM and CD24 were significantly higher in the ovarian cancer patients than in controls." (PMID 31212643, 2019). "Intriguingly, we also identified a subpopulation of EpCAM-positive cancer cells as possible candidates for ovarian cancer stem cells in an established mouse ovarian cancer model." (PMID 31261739, 2019). "In recent years, various specific markers of stemness, including CD44, CD117, aldehyde dehydrogenase (ALDH), CD133, CD24, and the epithelial cell adhesion molecule (EpCAM), have been used to isolate and characterize ovarian cancer stem cells." (PMID 31261739, 2019). "They demonstrated a 3–5-fold increase in EV-associated expressions of EpCAM, CA-125, CD9, CD81, and CD63 in ovarian cancer patients compared to healthy controls." (PMID 31212643, 2019). "We observed that ovarian cancer VM-associated cells were able to secrete SDC1 and B-FN and expressed the stem cell markers CD44 and EpCAM." (PMID 31443604, 2019). "In patients with ovarian cancer, EpCAM expression correlates with aggressiveness and metastatic extent." (PMID 30551640, 2018). "In ovarian cancer xenografts, cancer cells co-expressing EpCAM and CD44 or CD24 had stemness properties with resistance to doxorubicin and cisplatin." (PMID 30551640, 2018).
ovarian carcinoma (continued). "The bispecific CD44-EpCAM aptamer was significantly more effective than either single CD44 or EpCAM aptamer for inhibiting the cells growth or inducing apoptosis in ovarian cancer cells both in vitro and in vivo studies." (PMID 29747682, 2018). "Targeting EpCAM should be a promising approach to effectively extirpate the CSCs as the putative root of ovarian cancer." (PMID 28574829, 2017). "The exosomal EpCAM levels in normal individuals were very low, while an increase in the exosomal EpCAM level was found to be related to the stage and severity of ovarian carcinoma." (PMID 28506269, 2017). "In order to resolve these unanswered questions, we used Kaplan–Meier analysis to evaluate the capacity of EpCAM expression to predict clinical outcomes of ovarian cancer patients." (PMID 28574829, 2017). "The clinical significance of EpCAM was evaluated by immunohistochemical analysis using primary ovarian cancer tissues from 168 patients." (PMID 28574829, 2017). "For instance, epithelial cell adhesion molecule (EpCAM)-positive microvesicles were isolated from ovarian cancer for miRNA profiling." (PMID 28880270, 2017). "The principal findings of our study were that ovarian cancers containing high levels of EpCAM have a much lower probability of achieving ORR after first-line platinum-based treatment." (PMID 28574829, 2017). "In the present study, we demonstrated that increased expression of EpCAM contributes to resistance to platinum-based chemotherapy in ovarian cancer patients." (PMID 28574829, 2017). "In case primary ovarian cancer cells are present, these cells will be detected as E-cadherin, EMA, and EpCAM are virtually always expressed in ovarian cancer, and approximately 33% of primary ovarian carcinomas show Her2/neu amplification." (PMID 28327103, 2017). "There were significant differences in overall survival between the EpCAM-high and -low groups for patients with stage I–IV ovarian cancer." (PMID 28574829, 2017). "Immunofluorescence labeling of ovarian cancer cells with anti-EpCAM antibody showed various expression patterns of EpCAM." (PMID 28574829, 2017). "Three exosomal tumor markers (CA-125, CD24 and EpCAM) were used to isolate exosomes from ovarian cancer patient plasma." (PMID 29262670, 2017). "“ExoSearch” chip was used for liquid biopsy of ovarian cancer by measuring three exosomal tumor protein markers such as CA-125, EpCam and CD24." (PMID 28085080, 2017). "The expression of EpCAM on the surface of normal ovarian epithelium is very low but is increased in ovarian cancer with different histology." (PMID 28881822, 2017). "The expression of EpCAM on the surface of four human ovarian cancer cell lines, CAOV3, SW626, SKOV3-Luc, and PA-1, were examined with flow cytometry." (PMID 28088790, 2017). "Several tumor-associated antigens targeted with mAb for ovarian cancer have been identified, including NY-ESO-1, CA 125 (MUC16), MUC1, and epithelial cell adhesion molecule (EpCAM)." (PMID 29354116, 2017). "Anti-EpCAM monoclonal antibody (Catumaxomab) is useful for management of ovarian cancer with recurrent malignant ascites and can improve the quality of life (puncture-free time, time to next puncture)." (PMID 28881822, 2017). "Although reports of cellular and molecular properties of EpCAM in ovarian cancer are limited, EpCAM-positive ovarian cancer cells seem to possess CSC properties and play an important role in resistance to chemotherapy." (PMID 28574829, 2017). "In order to address these unresolved questions, we evaluated the correlation between EpCAM expression and overall survival and progression-free survival in patients with stage I–IV ovarian cancer." (PMID 28574829, 2017). "The 1615EpCAM TriKE was specific and active against EpCAM bearing ovarian cancer cells and mediated NK proliferation, sustained ADCC activity, improved lytic degranulation, and cytokine production." (PMID 29354116, 2017).
ovarian carcinoma (continued). "The present study was designed to elucidate the role of EpCAM in tumor resistance to chemotherapy and the potential relevance of EpCAM expression to the clinical outcomes of patients with ovarian cancer." (PMID 28574829, 2017). "In patients with stage III–IV ovarian cancer, overall survival and progression-free survival was statistically significantly shorter in the EpCAM-high group than in the EpCAM-low group." (PMID 28574829, 2017). "We then tested the enriched T cells stably expressing anti-EpCAM CAR for their anti-tumor cytotoxicity against human ovarian cancer cells." (PMID 28088790, 2017). "In conclusion, our present study represents the initial report showing EpCAM expression contributes to tumor resistance to chemotherapy in patients with ovarian cancer." (PMID 28574829, 2017). "Here we have demonstrated that ovarian cancers containing high levels of EpCAM have a significantly much lower probability of achieving overall responsive rates after first-line chemotherapy." (PMID 28574829, 2017). "This is illustrated by treatment with the bispecific antibody anti-EpCAM × anti-CD3 that eradicated PM from ovarian cancer in mice by reactivating tumour-resident T-cells." (PMID 27074785, 2016). "EpCAM has also been targeted as the putative marker of epithelial CSCs of ovarian cancer and pancreatic cancer." (PMID 27557490, 2016). "In patients with ovarian cancer, Taylor and colleagues identified a tumor-specific signature of eight miRNAs in EpCAM+ exosomes detectable in patient's plasma, as a disease-specific signature that discriminate cancer from benign ovarian disease." (PMID 26689993, 2016). "These signatures include EpCAM for colorectal and ovarian cancers, epidermal growth factor receptor (EGFR) for brain cancers and human epidermal growth factor receptor 2 receptor (HER2/neu) for breast cancer." (PMID 26604322, 2015). "Such a hybrid stage was described in human ovarian cancer cells freshly isolated from mouse xenografts, or, in situ, in human biopsies in which cancer cells simultaneously express the epithelial marker EpCAM and the mesenchymal marker vimentin." (PMID 26405433, 2015). "A trifunctional anti-EpCAM antibody (catumaxomab/Removab®), administered intraperitoneally to patients harboring ovarian carcinomas refractory to salvage chemotherapy, decreases tumor burden, ascites accumulation, and necessity of paracentesis." (PMID 26474755, 2015). "Human tumor-derived epithelial cell adhesion molecule- (EpCAM-) positive exosomes circulating in blood have been detected by specialized miRNA expression profiling as promising biomarkers of ovarian cancer and lung cancer." (PMID 25814782, 2015). "The interaction between CD44 and Oct4 has previously been described in squamous cell tumours, and EpCAM and CD44 have previously been implicated in malignant ovarian tumours." (PMID 26260289, 2015). "Catumaxomab, a trifunctional antibody directed against EpCAM, is a potent therapeutic agent for malignant ascites in EpCAM-positive advanced cancer (e.g., ovarian cancer)." (PMID 24895575, 2014). "This indicates that EpCAM can be useful as a biomarker for the diagnosis of ovarian cancer as well as the detection of tumor-derived exosomes." (PMID 24460816, 2014). "The Epithelial Cell Adhesion Molecule (EpCAM) is overexpressed in many cancers including ovarian cancer and EpCAM overexpression correlates with decreased survival of patients." (PMID 24489952, 2014). "Ovarian cancer cells exhibit over expression of the Epithelial Cell Adhesion Molecule (EpCAM) when compared with normal ovarian cells." (PMID 24489952, 2014). "Our MOC31PE immunotoxin binds to the cell surface antigen EpCAM, which is expressed by the majority of epithelial cancers including ovarian carcinomas." (PMID 24528603, 2014).
ovarian carcinoma (continued). "In addition, the direct association of EpCAM with the progression of ovarian cancer suggested that it may serve as potential therapeutic target for the treatment of ovarian cancer and different approaches have been established to target EpCAM." (PMID 24489952, 2014). "The ability to detect CA125 and EpCAM in the ascites of cellular aggregates of mouse xenografts is reflective of the data that we have observed in the NAD population of ovarian cancer patients." (PMID 23056490, 2012). "Using a novel purification method we demonstrate for the first time that tumor cells isolated from the ascites of recurrent ovarian cancer patients are enriched with EPCAM+++/STAT3+++ tumor cells compared to cells isolated from the ascites of CN patients." (PMID 23056490, 2012). "EpCAM has been shown to be an independent prognostic marker for reduced survival in ovarian cancer patients." (PMID 23056490, 2012). "Elucidating the regulation mechanisms of epcam in ovarian cancer as presented here thus opens up new possibilities to exploit EpCAM as a therapeutic target." (PMID 21694727, 2011). "Numerous studies confirmed the EpCAM overexpression in ovarian carcinomas, turning EpCAM into a well-established ovarian tumour marker." (PMID 21694727, 2011). "The cell line derived from the patient with ovarian cancer (EpCAM-CK+) was characterized by flow cytometry for expression of different stem cells markers and by Comparative Genomic Hybridization (CGH)." (PMID 21595914, 2011). "In two ascites specimens (colon cancer and ovarian cancer), CK+EpCAM- cells were detected, although EpCAM+CK+ positive cells were found in peripheral blood." (PMID 21595914, 2011). "Our results in ovarian cancer agree with previouslypublished reports of high expression of EPCAM localised to the membrane and highexpression of BIRC5 evenly distributed between the cytoplasm and nucleus." (PMID 21423607, 2011). "For example, catumaxomab is a trifunctional monoclonal antibody (anti-EpCAM × anti-CD3) approved to treat ovarian cancer patients with malignant ascites." (PMID 21694727, 2011). "Catumaxomab was also tested in a phase I/II dose-escalating study on 23 women affected by advanced ovarian cancer with symptomatic malignant ascites containing EpCAM+ tumour cells." (PMID 22235224, 2011). "Expression of EpCAM and DNA methylation (bisulphite sequencing) was determined for ovarian cancer cell lines." (PMID 21694727, 2011). "Exosomes in the ascites derived from ovarian cancer carried the marker set EpCAM, CD24 and CD9 that appear to exist on a common exosome type." (PMID 21651777, 2011). "In our ovarian cancer cell line panel, EpCAM expression was inversely correlated with the DNA methylation status of the promoter and part of exon 1, as reported for several other tumour types." (PMID 21694727, 2011). "In normal ovary and benign ovarian tumours, EpCAM expression is lower compared with malignant ovarian tumours." (PMID 21694727, 2011). "Its morphology and expression of EPCAM are consistent with an epithelial carcinoma, and like human ovarian carcinoma, it expresses her-2/neu, sex hormone receptors, and characteristic cytokines." (PMID 20356397, 2010). "It has been shown that the ovarian cancer proteins CD24 and EpCAM can indeed be found in exosomes from ascites fluid of ovarian cancer patients." (PMID 19619303, 2009). "One group has previously reported an approach, based upon EpCAM expression by ovarian cancer derived exosomes, for analysing exosomes present in the circulation." (PMID 19138409, 2009). "The CellSearch® system, currently the only Food and Drug Administration (FDA)-approved platform for circulating tumor cells isolation, employs EpCAM-based immunomagnetic enrichment technology, and CTCs provide a new way of thinking about diagnosing, treating, and following up on ovarian cancer." (PMID 40792273, 2025).
ovarian carcinoma (continued). "Furthermore, a CD73/epithelial cell adhesion molecule (EpCAM) bispecific antibody reduces proliferation in ovarian cancer cells and enhances sensitivity to chemotherapy." (PMID 41188606, 2025). "In contrast, OVCAR3, an ovarian cancer cell line, showed high expression levels of EpCAM." (PMID 40034272, 2025). "The first article in this field was published in 2010, which demonstrated that high-grade, drug-resistant ovarian cancer overexpresses epithelial cell adhesion molecule (EpCAM) and is highly sensitive to immunotherapy using MT201, a fully human monoclonal anti-EpCAM antibody." (PMID 40718421, 2025). "Notably, in one sample (PEM52), collected from an ovarian cancer patient, the majority of EpCAM+ cells were also positive for CD45." (PMID 40525275, 2025). "Considering only the NCCN-recommended ovarian cancer screening genes, it was noticed that no mutations were detected in the recommended EPCAM and STK11 genes." (PMID 38817903, 2024). "Overexpression of EpCAM in ovarian cancer differs based on the histological type." (PMID 38833451, 2024). "Furthermore, EpCAM+ ovarian cancer cells exhibited CSC characteristics of tumorigenicity and migration and were resistant to platinum-based chemotherapy." (PMID 38612911, 2024). "This makes EPCAM a promising biomarker for predicting response to chemotherapy in ovarian cancer." (PMID 40836974, 2024). "They collected ascites samples of ovarian cancer patients before and after treatment and observed that increased levels of exosomal EpCAM and CD24 in samples after treatment were associated with nonresponding patients." (PMID 38928484, 2024). "Newly emerging biomarkers for ovarian cancer include epithelial cell adhesion molecule (EPCAM), syndecans, R-spondin, and several G protein-coupled receptors (GPCRs), including the estrogen receptor GPER1, that are currently being investigated in pre-clinical studies." (PMID 40836974, 2024). "Moreover, the content of EpCAM-positive exosomes is positively correlated with cancer cell invasion, conferring on its a staging biomarker in ovarian cancer." (PMID 38791091, 2024). "Targeting EpCAM CAR-T cells exert antitumor effect in a mouse model of ovarian cancer." (PMID 38680498, 2024). "A surface plasmon resonance-based assay to detect exosomes was utilized to report elevated levels of epithelial cell adhesion molecule (EpCAM) and CD24 in exosomes from ascites of ovarian cancer patients, indicating their use as a diagnostic and prognostic biomarker." (PMID 39001524, 2024). "EpCAM, a well-studied biomarker, may have limitations in early-stage ovarian cancer detection, considering its potential cleavage from exosomes via serum metalloproteinase." (PMID 38201468, 2023). "Overall, these researchers suggested that EpCAM might act as a potent target antigen for CAR-T therapy of ovarian cancer; even though more in-depth assessments are required." (PMID 38146364, 2023). "Their results showed that EpCAM CAR T cells could become a clinical therapeutic strategy against ovarian cancer." (PMID 36707873, 2023). "Fourteen studies detected 29 cancers among 2224 women (1.3%), diagnosed between 35 and 83 years old.11 12 14 15 20 21 23–30 Twenty-eight of 1458 (1.9%) mismatch repair/EPCAM carriers were diagnosed with ovarian cancer, representing 96.6% of all ovarian cancers found." (PMID 35437274, 2022). "In addition, the expression of MC1-R and EpCAM in hybrid cells brings new perspectives as a possible marker for this phenomenon in ovarian cancer." (PMID 36499015, 2022). "Similarly, EpCAM+CD45+ ovarian cancer cells escaped NK-cell-mediated immune surveillance by overexpressing major histocompatibility complex class I antigen (MHC-I)." (PMID 36369033, 2022).